SCYGR5 (small cysteine and glycine repeat containing 5)
Description:
In the hair cortex, hair keratin intermediate filaments are embedded in an interfilamentous matrix, consisting of hair keratin-associated proteins (KRTAP), which are essential for the formation of a rigid and resistant hair shaft through their extensive disulfide bond cross-linking with abundant cysteine residues of hair keratins. The matrix proteins include the high-sulfur and high-glycine-tyrosine keratins.
Synonyms: KRTAP28-5
Gene: Protein-coding gene on chromosome 2 (227,666,804 to 227,667,061, forward strand). Ensembl gene ENSG00000284667.
Homologues: Orthologues: chimpanzee SCYGR5 (89% identical), pig SCYGR5 (71% identical).